PLIN2 (perilipin 2)
Diseases named in the same sentence as PLIN2 in open-access papers (continued):
Sharing a sentence is not in itself a finding about the gene and the disease.
Hepatic steatosis (continued). "Perilipin 2 (PLIN2), which positively correlates with hepatic steatosis, is one of the best-characterized LD proteins associated with fatty liver disease." (PMID 33608323, 2021). "However, after 24 weeks of HFD, the increase in PLIN2 was similar in female and male mice, where females displayed a more modest degree of hepatic steatosis than males, which could indicate that increased abundance of PLIN2 is promoted already in the early phases of hepatic steatosis development." (PMID 33193093, 2020). "We focused on molecules such as PLIN2 and NNMT, which were suggested by a proteomic analysis to be responsible for the effect of linagliptin on hepatic steatosis." (PMID 33105604, 2020). "The induction of perilipin 2 and PDK4 exemplifies the suitability of the in-vitro system to investigate drug candidates for the treatment of hepatic steatosis." (PMID 30547786, 2018). "ADFP (PLIN2), one of PLIN family member and well characterized protein in fatty liver disease, was increased in both 12M and 24M p21HBx/+ mice." (PMID 27708241, 2016). "The regulatory function of PLIN2 was illustrated by the observation that Plin2 knockout mice did not experience hepatic steatosis when exposed to an HFD." (PMID 41157845, 2025). "We examined Perilipin 2 (PLIN2), a lipid droplet protein whose hepatic expression increases in NAFLD and ALD and whose absence we have found to be protective against EtOH-induced hepatic steatosis." (PMID 37134024, 2023). "In hepatocytes, PLIN2 and PLIN3 are the major PAT protein family members that promote lipid storage, knockdown of each of which by antisense oligonucleotides can reduce diet-induced hepatic steatosis." (PMID 36107452, 2022). "The regulatory role of PLIN2 was demonstrated when Plin2 knockout mice did not develop hepatic steatosis in response to a high-fat diet." (PMID 33597924, 2020). "Here, we demonstrate that a global knockout of the cannabinoid receptor 1 gene (CB1−/−) reduced the expression of the lipid droplet binding protein PLIN2 in the livers of CB1−/− and hepatitis B surface protein (HBs)-transgenic mice, which spontaneously develop hepatic steatosis." (PMID 31570772, 2020). "PLIN2 knockout mice do not respond to diet-induced obesity, fatty inflammation, and hepatic steatosis." (PMID 30400205, 2018). "Most notably, absence of Plin2 prevented hepatic steatosis and ceramide accumulation in alcohol-fed mice." (PMID 24831094, 2014). "In contrast to their wild-type littermates, Plin2KO mice fed alcohol do not develop hepatic steatosis despite the presence of Plin3 (a lipid droplet protein shown to compensate for Plin2)." (PMID 24831094, 2014). "Hepatic quantitative proteomic and phosphoproteomic analyses revealed that perilipin-2 (PLIN2), major urinary protein 20 (MUP20), cytochrome P450 2b10 (CYP2B10), and nicotinamide N-methyltransferase (NNMT) are possibly involved in the process of the amelioration of hepatic steatosis by linagliptin." (PMID 33105604, 2020). "In addition, the absence of perilipin 2 in mice prevents alcohol-induced or diet-induced hepatic steatosis." (PMID 30477200, 2018). "In the present study, we aimed to determine whether an absence of Plin2 prevents the development of hepatic steatosis in alcohol-fed mice." (PMID 24831094, 2014). "Because the expression of CD36, DGAT2, and PLIN2 in liver is previously known to be regulated by PPARγ, a crucial nuclear transcription factor controlling cellular glucose and lipid metabolism, we also investigated whether PPARγ is involved in VPA-induced hepatic steatosis." (PMID 27034954, 2016). "The lack of hepatic steatosis and reduced hepatic triglyceride levels in Plin2KO mice result from multifactorial effects on cellular lipid homeostasis, namely, a downregulation of de novo lipogenic and triglyceride synthetic pathways and a lack of compensation for Plin2 by Plin1 and Plin3." (PMID 24831094, 2014).
Obesity (63 papers, 2013 to 2025). Accumulation of substantial excess body fat. "Their study underscores the role of Plin2 and cardiac lipid dysregulation in structural and electrical remodeling, providing insights into how obesity and metabolic disorders enhance AF risk." (PMID 39859272, 2025). "It has been reported that PLIN2 is accountable for lipid accumulation, and PLIN2−/− mice decreased the risk of diet-induced obesity." (PMID 39631563, 2024). "Two rare and deleterious variants disturbing the lipid-binding domain of the PLIN2 gene segregated with obesity in the two families." (PMID 33807278, 2021). "One of the recently studied molecules in non-alcoholic fatty liver disease associated with obesity, involving hyperlipidemia, hyperglycemia and insulin resistance is perilipin-2, a cytoplasmic protein that covers lipid droplets." (PMID 33968973, 2021). "RILP and FNIP2 were associated to a SI score > 20 and PLIN2 was associated with obesity in the two families." (PMID 33807278, 2021). "Conversely, obesity and glucose intolerance develop in mice with hepatic-specific deficiency of PLIN2 after 30 week Western-type diet feeding." (PMID 33923083, 2021). "Abca1 and Plin2 are marker genes for metabolically activated macrophages in response to obesity-associated cues." (PMID 34608215, 2021). "Whole-body loss or liver-specific loss of PLIN2 can prevent HFD-induced obesity, insulin resistance and NAFLD." (PMID 33912032, 2021). "Collectively, the data provide evidence of Plin2 regulated intestinal lipid uptake, which contributes to rapid changes in the gut microbial communities implicated in diet-induced obesity." (PMID 26147095, 2015). "PLIN2 plays a significant role in intracellular lipid metabolism and is associated with obesity." (PMID 40127054, 2025). "Notably, PLIN2 levels were significantly higher in female patients and varied significantly across obesity classes, suggesting potential clinical utility in risk stratification." (PMID 41515601, 2025). "Obesity caused by a high-fat diet also promotes the expression of PLIN2 in skeletal muscles." (PMID 38732501, 2024). "Furthermore, increased perilipin-2 is associated with body mass index and obesity, which are risk factors for both diabetic nephropathy and obesity-induced secondary FSGS." (PMID 36613637, 2022). "We next investigated whether hepatic PLIN2 deficiency could alter the onset or severity of comorbidities associated with NAFLD including obesity, insulin resistance and dyslipidemia." (PMID 33923083, 2021). "PLIN2 is known to be associated with the development of high-fat diet (HF)-induced obesity." (PMID 34579038, 2021). "Furthermore, we and others have shown that Plin2 deficiency protects against diet-induced obesity and insulin resistance." (PMID 24831094, 2014). "Given that perilipin content in adipocytes from obese individuals is typically low, the increase in PLIN2 observed in SCARB2 knockdown cells suggests that SCARB2 knockdown could potentially mitigate obesity risk by enhancing lipid droplet regulation and reducing fat accumulation." (PMID 40127054, 2025). "Furthermore, our study found a significant association between NAFLD status, obesity, and PLIN2." (PMID 41515601, 2025). "Because PLIN2 is described to be essential in the formation of cytoplasmic lipid droplets, we hypothesized that PLIN2 concentrations may be associated with obesity and established lipid markers." (PMID 34572396, 2021). "Furthermore, these studies imply that targeted loss of PLIN2 in one or more extra-hepatic tissues such as muscle, adipose, or brain may have therapeutic potential in the treatment of obesity associated weight gain and insulin resistance." (PMID 33923083, 2021). "It has been shown that the normal expression of Plin2 leads to increased obesity, while the deletion of Plin2 gene induces an obesity resistance phenotype in wild-type (WT) mice fed with a HFD to prevent the weight gain caused by the HFD." (PMID 40786039, 2025).
Obesity (continued). "Across obesity classes, PLIN2 levels differed significantly, with the main difference observed between class I and class II obesity." (PMID 41515601, 2025). "Expression of PLIN4, which can prevent lysosomal degradation of cytosolic lipid droplets, was increased with age in WT mice and by both ethanol and obesity in 3xTg‐AD mice, whereas PLIN2 and PLIN3, which promote lysosomal degradation, were reduced." (PMID 40677154, 2025). "Lipid droplets are key organelles for triglyceride storage in adipocytes, impaired degradation of PLIN2 in obesity can lead to abnormally enlarged lipid droplets, contributing to lipotoxicity." (PMID 40822952, 2025). "Proteins involved in lipid metabolism including ABCA1, CD36, and PLIN2 were reported to be specifically up-regulated in metabolically active macrophages in obesity." (PMID 40244655, 2025). "Proteomic profiling quantified identified 135 differentially expressed proteins (57 upregulated, 78 downregulated), with PHACTR2 and PLIN2 upregulated in obesity and ADAR down-regulated in obesity." (PMID 40822952, 2025). "Preclinical and some clinical studies have shown a relationship between PLIN2 overexpression and obesity, atherosclerosis, and Type 2 DM." (PMID 39062220, 2024). "Studies to characterize the role of hepatic Plin2 have primarily focused on its role in obesity and the development of nonalcoholic fatty liver disease caused by surplus energy intake." (PMID 37844775, 2023). "Our findings demonstrate that Plin2 is required to regulate hepatic LD size and storage of neutral lipid species in the fasted state, while its role in obesity-induced steatosis is less clear." (PMID 37844775, 2023). "Reduced Plin2 can prevent various metabolic disorders, such as obesity induced by a high-fat diet (HFD), IR, liver steatosis, adipose tissue inflammation, and T2DM." (PMID 34981123, 2022). "PLIN2-knockout mice show resistance to obesity and nonalcoholic steatohepatitis induced by a methionine-choline-deficient diet." (PMID 35742827, 2022). "In animals fed a high-fat diet, the deletion of the perilipin-2 gene prevented obesity, inflammation of adipose tissue, insulin resistance and steatosis." (PMID 33968973, 2021). "In the present study, our results agreed with previously published evidence, in which losartan decreased hepatosteatosis and PLIN2 in the liver of an obesity model." (PMID 34360607, 2021). "PLIN2 has been described to impair hepatic lipid accumulation and Plin2 whole body gene deletion prevented obesity and insulin resistance in Western diet-fed mice by suppressing hepatic SREBP-1/2 activity." (PMID 34867397, 2021). "The influence of oleic acid treatment on GSK3 activity suggests a potential regulatory role of PLIN2 during the interplay of intracellular lipid metabolism and cell functionality, which may support a biological mechanism of diseases risks associated with increased hyperlipidemia and obesity." (PMID 27493677, 2016). "We recently demonstrated that deletion of the Plin2 gene, largely abrogates the long-term effects of high fat (HF) diet induced obesity, insulin resistance, dyslipidemia, adipose inflammation, and NAFLD in mice." (PMID 26147095, 2015). "Our published studies have documented that Plin2 is required in the long term for high fat (HF) diet-induced obesity and fatty liver disease in mice." (PMID 26147095, 2015). "Expression of perlipin-2 (Plin-2) a gene involved in diet induced obesity and adipose inflammation was reduced in HYP-VE and WT-SPR4 mice but increased in HYP-SPR4 mice." (PMID 24839967, 2014). "Since Plin-2 null mice are protected against diet induced obesity, the decreased fat mass in HYP-VE mice is consistent with the reduced expression of Plin-2." (PMID 24839967, 2014). "However, a significant difference in PLIN2 levels was found when patients were stratified by obesity class." (PMID 41515601, 2025).
Obesity (continued). "Furthermore, Plin2-induced atrial steatosis exacerbated the effects of obesity and metabolic disorders on cardiac remodeling." (PMID 39859272, 2025). "Therefore, the expression of PLIN2 in the skeletal muscle of obesity-resistant mice further increased compared to that of obesity mice." (PMID 38732501, 2024). "However, the expression of PLIN2 in the skeletal muscles of obesity-resistant mice further increased." (PMID 38732501, 2024). "Our studies build upon this work, demonstrating that after 12 weeks of WTD feeding, deficiency of PLIN2 in hepatocytes fails to protect against the development of obesity and insulin resistance." (PMID 33923083, 2021). "One is intracellular lipid that sequesters PLIN2, which may provide a mechanism for the etiology of diseases such as Alzheimer’s disease, CVD and T2D that are often associated with obesity." (PMID 27493677, 2016). "In summary, our data suggest that Plin2 coordinates lipid homeostasis in the intestine, and that its effects on lipid uptake and transport by enterocytes modulate the capacity of the intestinal microbiome to contribute to diet-induced obesity and NAFLD." (PMID 26147095, 2015). "Interestingly, HF feeding, but not obesity, was associated with significantly lower Plin2 levels in mammary tissue (p<0.02)." (PMID 24849657, 2014). "Thus, identification of pathways that control expression of Plin2 may provide new therapeutic targets for the treatment of obesity and related disorders." (PMID 25102070, 2014). "Although this mechanism needs further experimental verification, it also provides a possible theoretical reference for the adjuvant therapy targeting PLIN2 in OSCC patients, especially those with the burden of obesity." (PMID 39875372, 2025). "Both perilipin 2 (PLIN2) and long-chain fatty acid transport protein 3 (SLC27A3) were found to be downregulated in myotubes from donors with obesity." (PMID 36467688, 2022). "On the contrary, three genes involved in angiogenesis and one involved in energy homeostasis were up-regulated in thew SAT of individuals with normal weight compared to individuals with obesity; DLL4, PLIN2, VEGFA and PNPLA2." (PMID 33022994, 2020). "To further characterize placental pathways for lipid storage and mobilization we focused on PLIN2, ATGL and CGI-58, which showed a strong positive correlation with maternal pre-gravid obesity." (PMID 27780978, 2017). "Perilipin-2 and Perilipin-3 shield droplet cores from lipases; Perilipin-2 is abundant in non-adipose tissues and correlates with steatosis—PLIN2-null mice exhibit lower hepatic TG and resist diet-induced obesity." (PMID 41149615, 2025). "Additionally, genes involved in white fat differentiation and adipogenesis pathways were downregulated by OJ consumption, including KLF4 (−2.3), RIPK1 (−1.7), PLIN2 (−1.99), and CXCL8 (−34.43); genes found as overexpressed in obesity." (PMID 41169019, 2025). "In sum, these data demonstrate that reduced hepatic PLIN2 does not protect against the development of HFD-induced weight and fat mass gain or obesity-associated alterations in insulin–glucose homeostasis early in the progression of NAFLD." (PMID 33923083, 2021). "Hyperlipidemia (i.e. high levels of extracellular lipids) and obesity (i.e. high levels of intracellular lipids) can increase GSK3 activity via (i) suppression/overstimulation of the PI3K/Akt pathway and (ii) dissociation of GSK3/PLIN2." (PMID 27493677, 2016). "PLIN2 might be a potential therapeutic target for OSCC patients, especially those with obesity." (PMID 39875372, 2025). "If the in vitro cell culture data can be extrapolated to in vivo situation such as hyperlipidemia/obesity (since GSK3 and PLIN2 are ubiquitously expressed), both acute and chronic lipid effects may generate over-suppressed and uncontrolled GSK3 activity, potentially causing divergent damages." (PMID 27493677, 2016).
Obesity (continued). "Therefore, given our result that PLIN2 protein is unchanged in CTSB-OE cells, it is likely that the obesity-induced upregulation of PLIN2 in WAT may be attributed to the increased infiltration of macrophages, rather than CTSB overexpression in obese adipocytes." (PMID 31959889, 2020).
steatosis (57 papers, 2012 to 2026). Increased lipid within the cytoplasm of cells. "PLIN2, a predominantly cytosolic protein expressed in the liver, has been implicated in the development of steatosis and insulin resistance." (PMID 41559682, 2026). "The prevention of steatosis and improvement of insulin resistance with the pharmacologic inhibition of ceramide synthesis are associated with reduced perilipin 2 (PLIN2), which is a lipid-droplet protein and is up-regulated in alcoholic steatosis." (PMID 35448380, 2022). "Of note, genetic targeting of lipid droplet associated proteins like Perilipin-2 (Plin2) and Fat-specific protein (Fsp27) have been reported to successfully attenuate steatosis and related features of steatohepatitis in murine models of alcohol feeding." (PMID 28946672, 2017). "An increase in Plin2 in liver is associated with the development of steatosis, glucose intolerance, and ceramide accumulation in alcoholic liver disease." (PMID 24831094, 2014). "When PLIN2, a member of the lipid droplet protein family, was inhibited, this was associated with a 548-fold increase in H19 levels accompanied by decreased liver TGs, suggesting a role for H19 in steatosis." (PMID 36203751, 2022). "Low levels of PLIN2 are associated with a lean phenotype and a reduced risk for steatosis in mice." (PMID 33372064, 2021). "This PLIN2-based reporter system provides a real-time platform for studying drug effects on steatosis but is limited to organoid models with high fat content and substantial PLIN2 expression, such as liver organoids." (PMID 40843351, 2025). "To assess the severity of MASH, we stained liver sections for steatosis marker perilipin-2 (PLIN2) and macrophage marker F4/80, and with antineutrophil antibody." (PMID 41448428, 2025). "A previous publication demonstrated a connection between the overexpression of PLIN2 in cardiomyocytes, steatosis and the remodeling of Cx43." (PMID 41511296, 2025). "Related research has shown that the overexpression of PLIN2 in the liver can induce steatosis of the liver." (PMID 38732501, 2024). "Temporal responses in Lpl, Plin2, and Nampt expression were more comparable between control and steatotic conditions, with more positive responses at 20 h, except for Nampt under steatosis conditions." (PMID 38920666, 2024). "The induction of Foxo1 and Plin2 was significantly stronger under steatosis compared to control conditions 20 h after synchronization." (PMID 38920666, 2024). "Recent research also found that dietary leucine and isoleucine ameliorate steatosis by promoting polyubiquitination of PLIN2 via powerfully binding to and activating UBR1, targeting the degradation of PLIN2." (PMID 39426289, 2024). "Treatment of hepatocytes with the long-chain fatty acids oleic acid or oleic + stearic acids led to steatosis as shown by Bodipy staining and increased expression of the steatosis marker perilipin 2 (PLIN2) mRNA." (PMID 38074511, 2024). "This is in agreement with previous findings indicating that high‐fat diet‐induced steatosis can be prevented by PLIN2 KO." (PMID 38650174, 2024). "Another study reported that perilipin 2 (Plin2) overexpression increased sustained AF in mice due to atrial steatosis." (PMID 37113690, 2023). "The development of the PLIN2 lipid reporter lines allows the combination of steatosis organoid models with automated imaging systems for higher-throughput drug and CRISPR screenings." (PMID 36823355, 2023). "A key role in the liver is also played by another gene, perilipin 2 (PLIN2; lfc = −3.63), a marker of steatosis, which is downregulated here." (PMID 37755981, 2023). "Impairment of CMA-mediated PLIN2 degradation disrupts cellular lipid homeostasis, which leads to diclofenac-induced steatosis and hepatotoxicity." (PMID 35265214, 2022).